IL1B (interleukin 1 beta)
Diseases named in the same sentence as IL1B in open-access papers (continued):
Sharing a sentence is not in itself a finding about the gene and the disease.
bacterial infection (continued). "The production of IL-1β, IL-1α, TNF-α, and IL-6 was completely dependent on bacterial infection, but low levels of MCP-1 and MIP-1α were already detected in the supernatants from uninfected cultures." (PMID 30455194, 2019). "The transcription of IFN-β, IL-1β and autophagy related genes (Atgs) were up-regulated in macrophages after treated with c-di-AMP or bacterial infection." (PMID 31333655, 2019). "SMER3 pretreatment of R848-primed BMDMs significantly decreased IL-1β and TNF-α production in response to bacterial infection." (PMID 29515583, 2018). "In this stage of bacterial infection, pro-inflammatory cytokines such as TNF-α, IL-1β, and IL-6 are elevated, playing a crucial role in the pathogenesis of acute bacterial infection." (PMID 30319993, 2018). "Bone-resorbing cytokines such as IL-1β, TNF-α, IL-6, and RANKL are produced in reaction to bacterial infections and induce ABL." (PMID 29670725, 2018). "Since A54970 strain failed to trigger IL-1β production, induced high levels of IL-10 and seems to be more susceptible than A28006 strain to microbicidal activity, we investigated the polarization of macrophages into M1 and M2 phenotype post bacterial infection." (PMID 30518854, 2018). "Sputum IL-1β concentrations are further increased in patients with AECOPD and show a strong correlation with bacterial infections." (PMID 28793896, 2017). "Further functional pathway analysis of differentially expressed genes in IL-1β-treated peripheral blood mononuclear cells highlighted the insufficiency of immune response in the child with PAP, especially the protection against bacterial infection." (PMID 28233860, 2017). "Comparable results regarding such high levels of IL1-β, TNF-α and IFN-γ were detected in pigs with viral respiratory disease and cattle with bacterial infection." (PMID 27547520, 2016). "Conversely, IL-4 DCs responded more to molecules involved in bacterial infection, such as flagellin (s=0.27), MDP (s=0.14), TNFα (s=0.39) or IL-1β (s=0.45)." (PMID 25335753, 2014). "Functionally assessed to have pro-inflammatory activity in fish, IL-1β and TNF-α are often co-expressed with other macrophage-derived inflammatory mediators such as IL-8, COX-2, and iNOS in parasitic and bacterial infections." (PMID 23865616, 2013). "In response to bacterial infection, dendritic cells produce IL-6, TGF-β, and IL-1β that drive IL-17 production from innate lymphocytes." (PMID 23469071, 2013). "It has been believed that RNase L regulates the production of several genes such as TNF-α, IL-1β, and IFN-β during viral and bacterial infection." (PMID 24324683, 2013). "We previously showed that human odontoblasts increased transcription of pro-inflammatory cytokines, IL-1β and TNF-α in response to bacterial infection in vitro." (PMID 21261944, 2011). "Consistent with the data presented in this study, TLR-4 signaling and activated macrophages are capable of producing and responding to IL-1β and TNF-α to fight against bacterial infection." (PMID 20565713, 2010). "This is in agreement with higher expression of CXCL5, IL1B, IL8 and TNF described for several bacterial infections, indicating that the immune system is activated to eliminate bacteria." (PMID 21176181, 2010). "In rat serum, IL-1β, IL-6, and TNF-α levels were significantly elevated, and increased internal bacterial infection and toxins were detected, implicating internal bacterial infection and toxin release as major factors in increased mortality after RCI." (PMID 41226494, 2025). "A positive association with other proinflammatory acute-phase proteins, such as interleukin 1β (IL1β) and interleukin 6 (IL6), has been observed in viral and bacterial infections in humans, although the sensitivity and specificity of this relationship require further clarification." (PMID 40218414, 2025). "Cytokines such as IL‐1β, IL‐2, IL‐5, IL‐6, IL‐8, IL‐12p70, IL‐17, and TNF‐α may be involved in the progression of COVID‐19 combined with bacterial infection." (PMID 39692539, 2024).
bacterial infection (continued). "In the aPDI groups, the expression of IL-1β was still observed, but IL-6 was almost not expressed, indicating that the bacterial infection had been controlled after aPDI." (PMID 38970013, 2024). "Platelet depletion did not significantly affect systemic IL-1β, TNFα, and IL-6 levels in mice, consistent with previous findings in LPS challenge and bacterial infection." (PMID 38977927, 2024). "Moreover, SP supplementation alone or mixed with Bacillus licheniformis enhanced the transcriptional levels of Lysozyme, Il-6, Il-1β, Tgf, and TNF-α, which in turn increased the goldfish resistance to bacterial infection and lowered its mortality rate." (PMID 39453066, 2024). "During bacterial infection, bacterial proteins in the cytoplasm are detected by NAIPs to activate the NLRC4 inflammasome, which results in the processing and activation of precursors of IL-1β and IL-18 cytokines for extracellular secretion." (PMID 36833425, 2023). "shinshuense, and found that mycolactone inhibited IL-1β secretion, but not IL-18, resulting in the exclusive induction of IL-18 by the bacterial infection." (PMID 37910490, 2023). "Importantly, TNFA, IL1B, and IL6 were up-regulated in response to the bacterial infections in both epithelial A549 and monocyte U937 cells, as well as in vivo in the lungs." (PMID 37686095, 2023). "Elevated concentrations of IL-1β, IL-6, and TNF-α in children may be correlated with OM; in particular, IL-6, a marker of a bacterial infection, can induce C-reactive protein (CRP) production and appears to play a vital role in inflammation in OM." (PMID 36911197, 2023). "Considering the CSF cell compositions, the CSF in the refractory stage contained fewer FFAR2+TNFAIP6+ NEUs and THBS1+IL1B+ MOs, which indicated that an immune response to a bacterial infection was not the main reaction to this condition." (PMID 36119025, 2022). "The activation of surface α-enolase trigger the production of inflammatory factors (TNFα, IL1β, IFNγ and PGE2) and could be detrimental for the pathology but could be beneficial during bacterial infection." (PMID 35154105, 2022). "In addition, MC degranulated and produced ROS, TNF-α, IL-1β, IL-6, IL-13 and MCP-1 in response to bacterial infection." (PMID 34194428, 2021). "Recently, it was reported that bacterial infections may activate silent nociceptors via cytokine production (including TNF-α and IL-1β), resulting in bladder hyperalgesia." (PMID 33574810, 2020). "The patient's BAL fluid had elevated IL-1β than in serum due to presence of bacterial infection, IFN-γ level was not confirmed." (PMID 33634060, 2020). "Both IL-1α and IL-1β were detectable in bronchioalveolar lavage fluids (BALs) of young children with CF in the absence of bacterial infection, highlighting potential for inflammation of the CF airway under sterile inflammation." (PMID 32765492, 2020). "On the other hand, SCFAs did not enhance the LDH release and IL-1β production in BMDMs without bacterial infection." (PMID 32991574, 2020). "Moreover, the upregulated levels of proinflammatory cytokines IL-1β, IL-6 and TNFα in the serum of mice infected by SL1344 manifested their stronger resistance to bacterial infection, which implied that the SL1344 had posed higher virulence to hosts." (PMID 30898022, 2019). "By utilizing an improved Tol2 transposon system, the transgenic fish has enhanced bacterial resistance against V. vulnificus and Streptococcus agalactiae and immunomodulatory effect was observed such as downregulation of IL-1β and TNF-α at 12 h post bacterial infection." (PMID 31824449, 2019). "The reduced expression of pro-inflammatory cytokines, such as IL-1β, IFN-γ and TNF-α, may also reflect the fact that bacterial infection was suppressed in BDL Tg mice." (PMID 30149550, 2018). "Collectively, these data indicate that respiratory viral infection, but not bacterial infection, elicits a robust release of IL-1β that is critically dependent on neutrophil recruitment." (PMID 29079611, 2018).
bacterial infection (continued). "Expression of pro-inflammatory cytokine genes such as il1b and tnfa is rapidly induced by many bacterial infections, and Shigella is no exception." (PMID 29881380, 2018). "In any case, the susceptibility of GSDMD and other GSDM deficient mouse strains to infectious agents and its comparison to mice lacking caspase-1, caspase-11, IL-1β, and/or IL-18 remains to be established, especially in non-bacterial infection contexts." (PMID 30459758, 2018). "As IL-1β secretion was unaffected by caspase-8 inhibition in both wt and nga(G330D) bacterial infection, our data suggest that neither inflammasome activation nor the regulation of IL-1β levels induced by GAS involve caspase-8 activity." (PMID 28720729, 2017). "This lack of an increase may be the result of excluding patients with presumptive bacterial infections, such as a low CRP level, because LPS is the main inducer of IL-1β synthesis." (PMID 29017522, 2017). "Notably, LPS injection induced il1b expression in myeloid cells, but not in the injured epidermal cells, suggesting that il1b induction by tissue injury occurs through a mechanism distinct from the mechanism underlying induction in myeloid cells following bacterial infection." (PMID 28229859, 2017). "We demonstrated that TNF-α secretion was downregulated in the presence of PDLF, however IL1-β production in response to bacterial infection was not significantly reduced." (PMID 28912533, 2017). "Since IL-1β is critical for host defense against bacterial infections in general, we investigated whether CLEC5A is required for IL-1β production in response to other bacteria." (PMID 28824166, 2017). "In the presence of bacterial infection for example, inflammation is normally triggered, and the subsequent release of MIF allows for prolonged inflammation through the release of other pro-inflammatory cytokines like TNF-α, IL-1β, IL-6, IL-8, IL-2, and IFN-γ." (PMID 26741693, 2016). "Here we show that caspase recruitment domain-containing protein 9 (CARD9), a protein associated with induction of proinflammatory cytokines by fungi, has a negative role on IL-1β production during bacterial infection." (PMID 27670879, 2016). "Since the IL-1β autocrine effects over mCx-I and ROS were observed in cell cultures in the absence of bacterial infections, the IL-1β autocrine effects appear to be a primary, intrinsic characteristic of CF cells." (PMID 24901709, 2014). "Moxifloxacin per se did not affect the levels of the inflammatory mediators IL-1β, KC (the functional homologue of IL-8 in mice) and IL-17A in the lungs of mice in the absence of bacterial infection." (PMID 25034539, 2014). "This is consistent with our findings that IL-1β tracks with bacterial infection and not influenza virus." (PMID 24324838, 2013). "Elevated IL-1β, IL-6, and IL-8 could be used to differentiate patients with suspicious IC/BPS and inflammatory reactions after bacterial infection." (PMID 24146927, 2013). "Primary cells treated with both Pam3CSK4 and GM-CSF showed increased intracellular levels of IL-1α and IL-1β protein, but did not release IL-1α and IL-1β, suggesting that primary human monocytes require an additional signal provided during bacterial infection to release IL-1 cytokines." (PMID 40470942, 2025). "Additionally, caspase-8 may also activate GSDMD and promote the maturation of IL1β and IL18, as observed in the context of bacterial infections." (PMID 41173854, 2025). "The expression levels of pro-inflammatory cytokines (il-1β and tnf-α) increased 6 h after bacterial infection, indicating that the fish is in a state of stress and is trying to cope with the bacterial infection, but it never returned during the duration of the experiment to control levels." (PMID 36838503, 2023).
bacterial infection (continued). "During the early phase of bacterial infection, NK cells mainly produce interferon-γ (IFN-γ), which can prime macrophage activation and contribute to potent innate immune responses, including the secretion of tumor necrosis factor α (TNF-α), interleukin 6 (IL-6) and interleukin 1β (IL-1β)." (PMID 33327533, 2020). "These independent studies suggest that pyroptosis might lead to extrusion of infected enterocytes and promote bacterial infection in vivo even in the absence of IL-1α, IL-1β, and IL-18." (PMID 30138458, 2018). "The same hypothesis could extend to OFX treatment, and the possibility that both PMB and OFX treatment synergizes with bacterial infection to augment IL-1β production should not be excluded." (PMID 28878761, 2017). "Another study revealed that bacterial infection induces carbon monoxide (CO) production in macrophages, which in turn promotes their bacterial killing and phagocytosis abilities both in vitro and in vivo through increasing the activation of NLRP3 inflammasome and the secretion of active IL-1β." (PMID 27980220, 2017). "Interestingly, IL-1β was mainly secreted after bacterial infection of HIBCPP and PMN TM, but not after stimulation of PMNs alone." (PMID 23448224, 2013). "The increased production of IL-1β was not due to increased cell death as there was no decrease in the viability of the neutrophils in the presence of S. aureus or MRSA compared with cultures without any bacterial infection." (PMID 23209417, 2012). "The influence of M. tuberculosis lipids on IL-1β expression may, therefore, be better investigated by live bacterial infections and our current findings do not exclude a significant role for these molecules in differential IL-1β expression." (PMID 21931620, 2011). "Serum cytokines including IL‐1β, IL‐2, IL‐5, IL‐6, IL‐8, IL‐12 p70, IL‐17, and TNF‐α were significantly higher in COVID‐19 patients with bacterial coinfections than those without bacterial infection." (PMID 39692539, 2024). "Upon bacterial infection, March5fl/fl BMDM promoted pro‐caspase‐1 cleavage and pro‐IL‐1β cleavage, whereas March5 cKO BMDM did not (Fig EV3G)." (PMID 37575012, 2023). "The mRNA levels of IL-1β and CXCL8 that were induced by bacterial infection were not changed in the presence of both pathogens." (PMID 28195157, 2017). "Compared with patients with other bacterial infections, those with β-haemolytic streptococcal infection had higher levels of IL-6, IL-10 and TNF-α but not a higher IL-1β level." (PMID 28176831, 2017). "Under certain conditions like bacterial infection of macrophages, another inflammasome, the NLRC4/Ipaf inflammasome, has been reported to downregulate autophagy independent of IL-1β production." (PMID 24456929, 2013). "In addition, plasma IL-1β and IL-6 were largely elevated in lactating sows by dietary intake of fish oil in the current study, which may be caused by the increase in MDA production instead of bacterial infection, as plasma CRP in lactating sows was not significantly influenced by fish oil intake." (PMID 40005899, 2025). "Although the importance of Caspase-1, and its target, IL1-β, in PMN activation and antimicrobial functions are not fully appreciated in different physiological contexts, our prior studies demonstrated that inflammasome activation in PMNs occurs during bacterial infection." (PMID 36191054, 2022).
cardiovascular disease (262 papers, 2007 to 2026). "In cardiovascular disorders, the production of adhesion molecules that cause vascular lesions is simulated by inflammatory cytokines, such as IL-1β and TNF-α." (PMID 40149874, 2025). "NLRP3, which has received the most study in cardiovascular disease, has been linked to increased IL-1β (IL1B) production and caspase-1 activity, as well as impaired cardiac function." (PMID 40332346, 2025). "In the context of cardiovascular diseases, IL-1β and its associated signaling responses are of interest, given the potential efficacy of IL-1β blockade (reviewed in12)." (PMID 40162230, 2025). "The NLRP3 inflammasome, a cytosolic complex found in pro-inflammatory immune cells, has been implicated in several cardiovascular diseases and is responsible for the processing and release of IL-1β using active caspase-1 (CASP1)." (PMID 39763850, 2024). "The meta-analysis highlighted that higher IL-1β levels correlate with an increased risk of adverse events, emphasizing IL-1β’s role as a key inflammatory mediator in cardiovascular diseases." (PMID 39057626, 2024). "In experimental models of cardiovascular disease, studies indicate that Tet2-deficient macrophages promote disease via enhanced production of IL-1β through the NLRP3 inflammasome." (PMID 39742155, 2024). "In summary, both IL-6 and IL-1β are integral to the inflammatory processes that underlie cardiovascular diseases." (PMID 39057626, 2024). "This process is driven by several inflammatory mediators which have been linked to cardiovascular diseases, including IL-1β, the NLRP3 inflammasome, NF-Kβ, and IL-6." (PMID 38275364, 2023). "Recent clinical trials indicate that targeting the prototypic pro-inflammatory cytokine IL-1β ameliorates the outcomes of cardiovascular disease, which is the first cause of death in T2D patients." (PMID 35276849, 2022). "Both end products of the activation of NLRP3, the cytokines IL-1β and IL-18, are pro-inflammatory and have been associated with several acute and chronic inflammatory diseases, including cardiovascular diseases." (PMID 35204152, 2022). "Patients with CV risk factors had increased levels of IL-1β and its gene expression signature and blocking IL-1β with canakinumab was observed to prevent recurrent cardiovascular disease (CVD)." (PMID 33868242, 2021). "For example, arterial stiffening in cardiovascular diseases is associated with an increase in IL-1β, IL-12, TNFα, and MCP-1 as measured from blood plasma." (PMID 32244521, 2020). "Exogenous IL-18 inhibits endothelial differentiation in control EPCs/CACs; IFN-α contributes to an elevated risk of cardiovascular disease through suppression of the IL-1β pathway." (PMID 32528469, 2020). "Of particular translational interest are their effects on interleukins especially on IL1-β, considering its prognostic role in cardiology and its correlation with an increased relative risk of cardiovascular disease." (PMID 30223482, 2018). "Interstingly, higher CVP and PWCP correlated with higher intrahepatic IL1B values (as shown by the postitive correlation with the ∆IL1B), indicating a potential link between the cardiovascular disease associated to NAFLD and the liver-specific inflammation." (PMID 26599575, 2015). "It has long been established that the development of chronic auto-inflammatory conditions, including RA and several cardiovascular diseases, is associated with elevated levels of pro-inflammatory cytokines such as IL-1β, IL-6 and TNF." (PMID 26474486, 2015). "Recent evidence suggests that IL-1β plays a key pathogenic role in many human conditions, including cardiovascular diseases, and in the central nervous system effects of exercise." (PMID 20175886, 2010). "Furthermore, treatment of empagliflozin in T2DM patients at high risk of cardiovascular disease led to a reduction in IL-1β secretion due to reduced NLRP3 inflammasome activation." (PMID 39843817, 2025).